PPP4R1 (protein phosphatase 4 regulatory subunit 1)
Description:
Regulatory subunit of serine/threonine-protein phosphatase 4. May play a role in regulation of cell division in renal glomeruli. The PPP4C-PPP4R1 PP4 complex may play a role in dephosphorylation and regulation of HDAC3. Plays a role in the inhibition of TNF-induced NF-kappa-B activation by regulating the dephosphorylation of TRAF2. (Microbial infection) Participates in merkel polyomavirus-mediated inhibition of NF-kappa-B by bridging viral small tumor antigen with NEMO.
Synonyms: MEG1; PP4R1; PP4(Rmeg)
Tractability: Antibody: the Human Protein Atlas places it where antibodies can reach. PROTAC: ubiquitination databases record sites on it; its protein half-life has been measured.
Gene: Protein-coding gene on chromosome 18 (9,546,791 to 9,615,240, reverse strand). Ensembl gene ENSG00000154845.
Subcellular location (Human Protein Atlas): Cytosol; Plasma membrane; Actin filaments; Calyx; End piece; Mid piece; Perinuclear theca; Principal piece
Gene Ontology:
Molecular function: protein binding; phosphoprotein phosphatase activity; protein phosphatase regulator activity
Biological process: protein phosphorylation; signal transduction
Cellular component: protein phosphatase 4 complex
Genetic constraint (gnomAD): Loss-of-function variants: 40 observed, 99.85 expected, observed/expected ratio (o/e) 0.4, 90% interval 0.31 to 0.52. The upper end of that interval is the gene's LOEUF score, 0.52, which puts it in group 2 of 6, group 1 being the genes least tolerant of losing a copy. Missense variants: 970 observed, 1,155.8 expected, observed/expected ratio (o/e) 0.84, 90% interval 0.8 to 0.88. Synonymous variants: 402 observed, 407.45 expected, observed/expected ratio (o/e) 0.99, 90% interval 0.91 to 1.07.
Homologues: Orthologues: chimpanzee PPP4R1 (99% identical), macaque PPP4R1 (97% identical), dog PPP4R1 (93% identical), rabbit PPP4R1 (92% identical), guinea pig PPP4R1 (87% identical), mouse Ppp4r1 (87% identical), rat Ppp4r1 (86% identical), pig PPP4R1 (85% identical), tropical clawed frog ppp4r1 (76% identical), zebrafish ppp4r1 (32% identical), Caenorhabditis elegans ppfr-1 (17% identical), Drosophila melanogaster Pp2A-29B (16% identical). Paralogues in human: PPP2R1A (17% identical), PPP2R1B (17% identical).
Diseases named in the same sentence as PPP4R1 in open-access papers:
PPP4R1 is named in the same sentence as 16 diseases in open-access papers, as found by Europe PMC text mining. Sharing a sentence is not in itself a finding about the gene and the disease. The quoted sentences say what the papers report.
leukaemia (2 papers, 2017 to 2022). "The present study investigates the role of the protein phosphatase 4 regulatory subunit 1 (PP4R1) in leukaemia." (PMID 36544136, 2022). "Additionally, qRT-PCR analyses of the other PPP4 regulatory subunits Ppp4r1, Ppp4r3a, and Ppp4r3b were performed to validate specific knockdown of Ppp4r2 in the MLLT3-KMT2A leukemia model." (PMID 29221109, 2017).
non-small cell lung carcinoma (2 papers, 2021 to 2024). A group of at least three distinct histological types of lung cancer, including non-small cell squamous cell carcinoma, adenocarcinoma, and large cell carcinoma. "In non-small cell lung cancer (NSCLC), the protein phosphatase 4 regulatory subunit 1 (PPP4R1) interacts with HMGA2 to promote cell migration and metastasis via activating EMT." (PMID 38361784, 2024).
breast carcinoma (1 paper, 2010). "Only the downregulated expressions of ZFP161, PPP4R1 and YES1 were correlated with the luminal B subtype suggesting their potential involvement in the genesis of a particularly aggressive form of breast cancer with 18p loss." (PMID 20698951, 2010).
breast tumors (1 paper, 2010). "We have also pointed to other 18p TSG candidates including ZFP161, CEP76, PPP4R1 and PTPN2 whose involvement might explain the aggressive phenotype of breast tumors with 18p loss." (PMID 20698951, 2010).
Cirrhosis (1 paper, 2023). A chronic disorder of the liver in which liver tissue becomes scarred and is partially replaced by regenerative nodules and fibrotic tissue resulting in loss of liver function. "No explicit investigation has established a direct link between PPP4R1 and the onset of cirrhosis." (PMID 37808522, 2023). "Therefore, there should also be a relationship between the upregulation of PPP4R1 expression and the formation of cirrhosis." (PMID 37808522, 2023). "Moreover, ITGBL1, LOXL1 and PPP4R1 are all significantly enriched in the Ribosome pathway, so these three genes may also influence the formation of cirrhosis by regulating ribosome function." (PMID 37808522, 2023).
cancer (2 papers, 2021 to 2025). A tumor composed of atypical neoplastic, often pleomorphic cells that invade other tissues. "Lastly, the protein phosphatase 4 regulatory subunit 1 (PPP4R1) has been reported to be involved in cancer development, especially with poor prognosis, drug resistance, and natural killer cell‐mediated toxicity." (PMID 40364472, 2025).
PPP4R1 also shares sentences with these, for which no sentence is quoted: Insulin resistance (2 papers); Autoimmunity (1); colorectal cancer (1); cutaneous T cell lymphoma (1); gastric cancer (1); liver cancer (1); migraine (1); thyroid disease (1); Tumour (1); type 2 diabetes mellitus (1).